FOXP1 (forkhead box P1)
Diseases named in the same sentence as FOXP1 in open-access papers (continued):
Sharing a sentence is not in itself a finding about the gene and the disease.
glioma (20 papers, 2014 to 2022). A benign or malignant brain and spinal cord tumor that arises from glial cells (astrocytes, oligodendrocytes, ependymal cells). "In a word, these results yielded that STAT3 and FOXP1 may be underlying therapeutics for glioma." (PMID 30134017, 2018). "For example, it has been reported that STAT3 contributes to tumor progression by promoting FOXP1 transcription in glioma." (PMID 35432536, 2022). "FOXP1/FOXP2 are overexpressed since the upregulated molecule circ-SHKBP1 in glioma wound sequester their hunters-miR-544a/miR-379." (PMID 32518520, 2020). "Another study indicated the involvement of circ-SHKBP1 in angiogenesis of glioma-exposed endothelial cells via miR-544a/FOXP1 and miR-379/FOXP2 pathways." (PMID 32549760, 2020). "circ-SHKBP1 regulated the angiogenesis of glioma-exposed endothelial cells through the miR-544a/FOXP1 and miR-379/FOXP2 Pathways." (PMID 31214170, 2019). "MiR-101-3p and miR-195 were found to be putative targets of SNHG12, which inhibited the progression of glioma by down-regulating their target genes, Forkhead Box Protein P1 (FOXP1), and Sry-Box 5 (SOX5)." (PMID 31620362, 2019). "In human glioma, miR-504 suppressed cell proliferation and induced cell apoptosis by targeting Forkhead Box P1 (FOXP1)." (PMID 30953094, 2019). "STAT3 promoted cell proliferation, inhibited cell apoptosis and enhanced cell invasion through promoting FOXP1 transcription in glioma cells." (PMID 30134017, 2018). "The expression of circ-SHKBP1 is elevated in glioma-exposed endothelial cells (GECs), which functions as a ceRNA via the miR-544a/FOXP1 or miR-379/FOXP2 pathway." (PMID 30111313, 2018). "Our findings facilitate the perception of molecular mechanism and effects of STAT3 on glioma progression via inducing FOXP1 and usher in a novel therapy for gliomagenesis." (PMID 30134017, 2018). "What's more, FOXP1 was reported by Tian et al45 to be an oncogene by increasing cell growth in glioma cells." (PMID 30134017, 2018). "Quantitative real‐time PCR (qRT‐PCR) and Western blot assay were administered to assess the mRNA and protein expression levels of STAT3 and FOXP1 in glioma tissues and cells, respectively." (PMID 30134017, 2018). "This molecular mechanism between STAT3 and FOXP1 can serve as a therapeutic target for glioma treatment." (PMID 30134017, 2018). "Gomez et al46 also held that downregulation of miR‐9 upregulated FOXP1 to promote tumorigenicity in glioma cells." (PMID 30134017, 2018). "This was the first time that the molecular mechanism between STAT3 and FOXP1 in glioma cells was discussed." (PMID 30134017, 2018). "Cui and his colleagues identified FOXP1 as a direct target of miR-504 in glioma tumorigenesis and showed that miR-504/FOXP1 signaling significantly decreases cellular invasiveness and inhibits lymph node metastasis." (PMID 27999212, 2017). "STAT3 contributes to glioma progression by promoting FOXP1 transcription." (PMID 35432536, 2022). "Overexpression of FOXP1 inhibits proliferation and invasion in Glioma." (PMID 36203616, 2022). "Therefore, circ-SHKBP1 promoted the movement and tube formation of glioma-exposed endothelial cells to boost angiogenesis via the circ-SHKBP1/miR-544a/FOXP1 and circ-SHKBP1/miR-379/FOXP2 axis." (PMID 32518520, 2020). "Hence, circ-SHKBP1 modulated glioma angiogenesis through targeting miR-544a/FOXP1/AGGF1 and miR-379/FOXP2/AGGF1 pathway." (PMID 32061256, 2020). "Taken together, these findings suggest that SNHG12 acts as a key player in the progression of glioma by its involvement in the miR-101-3p/FOXP1 axis, and the miR-195/SOX5 axis, which are stabilized by the binding of the RNA-binding proteins, HuR and TDP43, respectively." (PMID 31620362, 2019). "In addition, lncRNA MALAT1 and SNHG12 promoted proliferation of multiple myeloma and glioma targeting FOXP1, while lncRNA UFC1 and 7SL enhanced proliferation of cervical cancer and osteosarcoma, targeting FOXP3 and FOXP4, respectively." (PMID 31815635, 2019).
glioma (continued). "Additionally, reducing glioma cell viability dramatically induced by STAT3 inhibition was rescued via FOXP1 upregulation." (PMID 30134017, 2018). "Given that, STAT3 expression was depleted by transfection with small interfering RNA (siRNA) in glioma cells, in an attempt to elaborate whether STAT3 has a certain bearing on FOXP1 in glioma cells." (PMID 30134017, 2018). "Up to now, however, the associations between STAT3 and FOXP1 expression in human glioma have not been examined." (PMID 30134017, 2018). "To determine whether STAT3 promoted glioma progression via FOXP1 induction, we performed rescue experiment in U87 and SHG‐44 cells." (PMID 30134017, 2018). "Forkhead box protein P1 (FOXP1) is a target of miR-504 in glioma." (PMID 27999207, 2017). "Furthermore, our recent study demonstrated that miR-504 could inhibit cell proliferation and promote apoptosis by targeting FOXP1 (forkhead box P1) in glioma cells." (PMID 31419987, 2019). "In addition, the expression of circ-SHKBP1 is elevated in glioma-exposed endothelial cells (GECs), and promotes the viability, migration and tube formation of GECs via the miR-544a/FOXP1 or miR-379/FOXP2 pathway via the AGGF1 itself or though the PI3K/AKT and ERK 1/2 pathways." (PMID 30111313, 2018). "Furthermore, in our rescue experiments, we explored whether the downregulation of STAT3 alters the biological function of glioma cells by inducing FOXP1." (PMID 30134017, 2018). "However, less report has dealt with the direct correlation of STAT3 and FOXP1 in glioma cells." (PMID 30134017, 2018). "Circ-TTBK2 regulated the miR-217/HNF1b/Derlin-1 pathway to promote the progression of glioma; and circ-SHKBP1 regulated the angiogenesis of U87 glioma-exposed endothelial cells through miR-544a/FOXP1 and miR-379/FOXP2 pathways." (PMID 31179240, 2019).
hepatocellular carcinoma (18 papers, 2013 to 2025). A malignant tumor that arises from hepatocytes. "FOXP1 is downregulated in human glioma, hepatocellular carcinoma (HCC), and esophageal squamous cell carcinoma." (PMID 40672953, 2025). "FOXC1 and FOXC2 were required for intestinal regeneration by stimulating paracrine CXCL12 and Wnt signaling, and FOXP1 downregulation inhibited G1/S phase cell cycle arrest by inducing the proliferation of hepatocellular carcinoma." (PMID 38192721, 2023). "It has been demonstrated that silencing FOXP1 significantly inhibits the proliferation of hepatocellular carcinoma cells in vitro and in vivo." (PMID 37035153, 2023). "circRNA circHipk2 expression in C2C12 myoblasts is mediated by Sp1, and circ-FOXP1 in hepatocellular carcinoma cells is regulated by SOX9." (PMID 35832649, 2022). "In conclusion, downregulation of FOXP1 inhibits cell proliferation in hepatocellular carcinoma by inducing G1/S phase cell cycle arrest, and the decrease in phosphorylated Rb is the main contributor to this G1/S phase arrest." (PMID 27618020, 2016). "In conclusion, our study emphasizes that downregulation of FOXP1 is able to inhibit cell proliferation in hepatocellular carcinoma via inducing G1/S phase cell cycle arrest, in which the decrease of phosphorylated Rb is the main contributor." (PMID 27618020, 2016). "FOXP1 can affect cell proliferation and migratory ability in hepatocellular carcinoma (HCC) in vitro." (PMID 27618020, 2016). "CircFoxp1 is a 587 bp circular RNA consisting of Foxp1 exons 8–11 and is involved in mesenchymal stem cell differentiation and hepatocellular carcinoma cell proliferation and metastasis, We here found that circFoxp1 recruited DNMT1 by binding to its host gene Foxp1 promoter." (PMID 32951006, 2020). "Consistent with the overexpression of IRs in human melanoma, lymphoma, hepatocellular carcinoma and gastric cancer, our results show that mRNAs encoding PD-1, TIM-3, BTLA and Foxp1 are also upregulated in CD8+ T cells isolated from spleens of mice-bearing mouse 4T1 breast tumours." (PMID 31594465, 2019). "Interestingly, FoxP1 expression has been shown to be altered by the hypomethylating agent 5-azacytidine and by micro RNA expression neighboring the FoxP1 gene in human hepatocellular carcinoma cell lines." (PMID 24937757, 2014). "In addition, it has been shown that FOXP1 can affect the activation of the TGF-β pathway by binding to the transcription factors Smad2 and Smad3, thereby causing CD8+ T cells de-lymphotoxicity in hepatocellular carcinoma tissues." (PMID 37035153, 2023). "For example, the expression of the circular RNA circ-FOXP1 was remarkably upregulated in hepatocellular carcinoma (HCC) tissues, and this upregulated circFOXP1 was induced by SOX9, which promoted HCC progression through sponging to miR-875-3p and miR-42124." (PMID 38745044, 2024). "Additionally, in hepatocellular carcinoma (HCC), two SOX9 binding sites have been identified in the promoter region of FOXP1." (PMID 39606233, 2024).
lymphoma (17 papers, 2013 to 2025). A malignant (clonal) proliferation of B- lymphocytes or T- lymphocytes which involves the lymph nodes, bone marrow and/or extranodal sites. "Among the prominent genes associated with this topic, we focus on the master regulator FOXP1, an essential gene in development which has been associated with several cancers, including lymphoma." (PMID 38395871, 2024). "FOXP1 overexpression defines a group of lymphomas with a poor-prognosis, but the underlying molecular mechanism remains to be elucidated." (PMID 37576391, 2023). "In summary, our meta-analysis suggests that decreased expression of the FOXP1 protein is associated with better survival in patients with lymphomas but poorer survival in patients with solid tumors." (PMID 27457567, 2016). "Overall, decreased expression of FOXP1 protein was associated with favorable overall survival (OS) in lymphoma patients (HR = 0.38, 95%CI: 0.30–0.48, p < 0.001)." (PMID 27457567, 2016). "The deregulation of FOXP1 expression plays an important role in lymphoma development, although the underlying molecular mechanism is poorly understood." (PMID 24887414, 2014). "Meanwhile, when GINS1 was overexpressed by lentivirus infection in these cells, GINS1 upregulation restored DOX resistance in lymphoma cells suppressed by FOXP1 silencing." (PMID 37576391, 2023). "FOXF1, FOXK2, FOXO1, FOXO3, and FOXP1 were differentially expressed in at least five subtypes of lymphoma." (PMID 36292640, 2022). "This A20 Foxp1 CRISPR model should prove valuable for studying the contribution of Foxp1 to immune evasion in aggressive lymphoma." (PMID 32309216, 2020). "Upregulation of MHC-II improves the presentation of lymphoma antigens, making T cells a likely candidate for contributing to the Foxp1 depletion phenotype." (PMID 32309216, 2020). "The A20 Foxp1 CRISPR model will help to further characterize the contribution of Foxp1 to lymphoma immune evasion and the potential for Foxp1 targeting to synergize with other immunotherapies." (PMID 32309216, 2020). "Further studies are needed to comprehensively explore the immunological mechanisms by which Foxp1 impairs lymphoma growth." (PMID 32309216, 2020). "In summary we have developed an in vivo A29 lymphoma model in which stable Foxp1 depletion by CRISPR/Cas9 genome editing delayed in vivo lymphoma growth and appeared to be curative in a subgroup of animals." (PMID 32309216, 2020). "Using CRISPR/Cas9 genome editing we have depleted Foxp1 expression in the aggressive murine A20 lymphoma cell line." (PMID 32309216, 2020). "It is interesting that decreased expression of FOXP1 had different prognostic values for lymphomas and solid tumors." (PMID 27457567, 2016). "When the subgroup analyses were conducted, the pooled results demonstrated that decreased FOXP1 expression was a favorable prognostic factor for lymphomas but an unfavorable factor for solid tumors." (PMID 27457567, 2016). "Following QRT-PCR data, we applied primers for exon 7, which was the first commonly upregulated coding exon of FOXP1 in these lymphomas, and expected to identify flanking upstream sequences." (PMID 24416450, 2014). "Their identification, however, requires further molecular studies performed on large series of FOXP1-positive lymphomas." (PMID 24416450, 2014). "Both index cases and FOXP1-positive lymphomas (except of case 7) revealed a low expression of exons 3/4 and 5/6 and an increased expression of exons 7/8 and onwards compared to exons 5/6." (PMID 24416450, 2014). "Noteworthy, FOXP1 is targeted by rare but recurrent chromosomal translocations in lymphoma, particularly MZL and DLBCL." (PMID 24416450, 2014). "FOXP1 is a long gene (approximately 600Kb) with a complex transcriptional architecture, expressing several isoform; excess abundance of a short isoform has been reported to be a marker for lymphoma." (PMID 38395871, 2024). "Downregulation of FOXP1/GINS1 significantly sensitized lymphoma cells to doxorubicin." (PMID 37576391, 2023).
lymphoma (continued). "In an in vivo xenograft lymphoma mouse model, the FOXP1/GINS1 regulatory axis was also validated." (PMID 37576391, 2023). "To experimentally test this hypothesis we have used CRISPR/Cas9 genome editing to deplete Foxp1 from an immune competent lymphoma model." (PMID 32309216, 2020). "The role of FOXP1 in human lymphoma has mostly been studied in DLBCL cell lines." (PMID 27806315, 2017). "First, decreased FOXP1 protein expression may be a universal favorable prognostic factor for lymphomas." (PMID 27457567, 2016). "Third, FOXP1 protein may function as a tumor promoter in lymphomas and act as a tumor suppressor in solid tumors." (PMID 27457567, 2016). "While FOXP1 positively regulates the expression level of GINS1 in DLBCL and promotes DLBCL proliferation, we found that the GINS1 level was not reduced in FOXP1-deficient H1975 cells or HEK293T cells, indicating the different functions of FOXP1 in lymphoma and solid tumors." (PMID 39623140, 2025). "Thus, we speculate that decreased FOXP1 protein expression may have similar prognostic value for all types of lymphoma that originate from lymphocytes." (PMID 27457567, 2016). "In summary, this study first demonstrated that FOXP1 and its target gene GINS1 contribute to DOX resistance in lymphoma cells." (PMID 37576391, 2023). "In DLBCL cell lines, FOXP1, directly represses TP63 and cooperate with NF-κB signaling to promote lymphoma cell survival." (PMID 26878872, 2016). "FOXP1 was already described as fused to either the PAX5 or the ABL1 gene in B-ALL, and to the immunoglobulin heavy chain locus in lymphomas." (PMID 24893616, 2014). "Thus, in contrast to our in vitro studies with pure lymphoma cell populations, primary DLBCL biopsies containing the tumor cells and their microenvironment exhibit a relationship between MHC II and FOXP1 gene expression independently of COO subtype." (PMID 26500140, 2016). "RNA-sequencing of a few lymphoma cases expressing FOXP1NT and FOXP1FL detected neither FOXP1-related fusions nor FOXP1 mutations." (PMID 24416450, 2014). "FOXP1-negative lymphomas showed an enhanced expression of exons 7/8–17/18 (cases 15 and 16), which likely reflected expression of FOXP1 by residual non-malignant cells." (PMID 24416450, 2014). "Therefore, we presume that FOXP1, like BCL2, may require additional genetic hits to initiate lymphoma." (PMID 24416450, 2014). "The improved survival of NOD SCIDγ mice bearing the Foxp1 exon 7 A20 clone may reflect the more complete ablation of Foxp1 expression and is consistent with the in vitro ability of Foxp1 to modulate multiple pathways with an important role in lymphoma pathogenesis, not just immune surveillance." (PMID 32309216, 2020). "Here, we show that Foxp1 silencing increases cell surface MHC-II (I-Ab in BALB/c mice) expression, and significantly impairs A20 lymphoma growth in vivo in an immune-competent but not an immunocompromised host." (PMID 32309216, 2020).
developmental delay (16 papers, 2010 to 2025). "Mutation or haploinsufficiency of the FOXP1 gene has been implicated in FOXP1 syndrome, a neurodevelopmental disorder characterized by developmental delay, ID, speech and language impairment, different levels of cognitive abilities, and behavior abnormalities." (PMID 41156002, 2025). "Although difficulties with fine motor movement and co-ordination are sometimes present in DVD patients with FOXP2 mutations, gross motor and developmental delay appear to be more predominant in patients with FOXP1 disruption." (PMID 22736078, 2012). "Compared to the clinical findings in our patients, there is a clear overlap with regard to the speech and developmental delay suggesting that haploinsufficiency of FOXP1 is indeed causative for this phenotype." (PMID 20848658, 2010). "However, the child also presented with developmental delays and speech and language deficits, which the authors hypothesized might be caused by the disruption of FOXP1." (PMID 20955937, 2010). "Further genetic analysis identified a de novo heterozygous FOXP1 frameshift variant (c.1240_1241del and p.Leu414Aspfs∗45), consistent with FOXP1 syndrome, a neurodevelopmental disorder characterized by global developmental delay and autistic features." (PMID 40488176, 2025). "Genetic testing for individuals with ID, ASD, or developmental delay, in addition to CMA, involves next-generation sequencing, which should be used to test for FOXP1 sequence variants." (PMID 33892622, 2021). "A review of the DECIPHER database revealed a similar-sized deletion disrupting FOXP1 in an individual with developmental delay, sensorineural deafness, hypotonia, club foot, and dislocation of hip." (PMID 22102821, 2011). "This investigation identified deletions of the FOXP1 gene in three unrelated patients (two males, one female) with moderate learning disabilities, global developmental delays, and severe speech and language disorders." (PMID 20955937, 2010). "The authors optimistically attributed many of the patient’s symptoms including the speech delay to the disruption of FOXP1, but the contribution of PROK2 and GPR27 to the phenotype cannot be ruled out, especially considering that both genes were previously implicated in developmental retardation." (PMID 22736078, 2012). "In addition, individuals with FOXP1 deletions, truncating variants, and missense variants did not have significant differences in the severity of developmental delay." (PMID 33892622, 2021). "CMA is used as a first-tier test for individuals with ID, ASD, or developmental delay and identifies individuals with FOXP1S due to 3p14 deletions which include the FOXP1 gene." (PMID 33892622, 2021).